ASCL2 (achaete-scute family bHLH transcription factor 2)
Diseases named in the same sentence as ASCL2 in open-access papers (continued):
Sharing a sentence is not in itself a finding about the gene and the disease.
colon cancer (continued). "Enrichment of Lgr5 and Ascl2 expression in the colon tumors of infected miR-34a-/- mice was further confirmed by western blot." (PMID 30543324, 2018). "The colon stem cells, marked by the Wnt signaling enhancers Lgr5 and Ascl2, are usually confined at the base of the crypt in wild-type and miR-34a-/- mice but became enriched in C. rodentium-induced colon tumors in miR-34a-/- mice." (PMID 30543324, 2018). "A correlation between YAP1 and Ascl2 was present not only in the CD133+CD44+ CRC cell population but also in colon cancer tissue samples." (PMID 29312609, 2017). "Taken together, we suggest that YAP1/KLF5-activated Ascl2 expression in colon cancer progenitor cells confers their self-renewability." (PMID 29312609, 2017). "The accordant increase of YAP1 and Ascl2 in human colon cancer samples was consistent with the observations in vitro." (PMID 29312609, 2017). "Commonly repressed genes included the colon and colon cancer stem cell genes ASCL2 and LGR5 as well as EPHB2, SOX4 and P21, all as compared with control cells after normalization with housekeeping genes." (PMID 24920608, 2014). "Western blot analysis demonstrated that Ascl2 was present in both colon cancer cell lines HT-29 and LS174T cells (20 kDa in both), but absent in MHCC-97L, a liver cancer cell line." (PMID 22384170, 2012). "An increase in Ascl2 protein expression in the nucleus of colon cancer cells of human colon cancers was observed when compared with the specific staining of Ascl2 protein at the nucleus of crypt base cells of normal colon mucosa." (PMID 22384170, 2012). "The cell line HT-29 (47.5–95% of CD133+ population) and LS174T (0.45% of CD133+ population) were chosen for functional evaluation of Ascl2 in colon cancer progenitor cells after gene knockdown by RNA interference." (PMID 22384170, 2012). "HMGA1 upregulates ASCL2 and promotes oncogenic properties in human colon cancer cells." (PMID 39895630, 2025). "To determine whether ASCL2 restoration will rescue these phenotypes, we reexpressed ASCL2 in both colon cancer cell lines (SW620 and SW480) with HMGA1 silencing." (PMID 39895630, 2025). "Most importantly, both HMGA1 and ASCL2 are coexpressed and upregulated in human colon cancer." (PMID 39895630, 2025). "Because our results strongly link HMGA1 to ASCL2 in colon tumorigenesis in humans and mice, we tested whether HMGA1 directly activates ASCL2 expression in human colon cancer cells." (PMID 39895630, 2025). "Moreover, PAF1 knockdown decreased the expression levels of the genes such as LGR5, ID1, ID3, CD44v9, CD133, BMI1, RNF43, EPHB2, SOX9, and ASCL2, which are critical for inducing colon cancer stemness and its markers." (PMID 38182897, 2024). "Given most reports indicated that ASCL2 was involved in the development of colon cancer as a transcription factor, we first explored whether ASCL2 regulated the expression of DPEP1." (PMID 35670012, 2023). "Interestingly, we found that ASCL2 expression was significantly positively correlated with that of DPEP1 in colon cancer tissues." (PMID 35670012, 2023). "In conclusion, ASCL2 upregulated DPEP1 expression levels in colon cancer cells." (PMID 35670012, 2023). "MTT assays were used to evaluate the role of DPEP1 and ASCL2 in colon cancer drug resistance." (PMID 35670012, 2023). "As a result, stem cell markers of CD44V showed remarkable increase of their expression in primary colon tumor tissues like Ascl2, but not associate with aggressive phenotypes of colon cancer at all." (PMID 37098074, 2023). "Second, ASCL2 (Achaete-scute homolog 2) is an essential helix-loop-helix transcription factor and a cancer stem cell marker, and specific reports have revealed that ASCL2 promotes cell proliferation and migration in colon cancer." (PMID 36936373, 2023). "There was a significantly positive correlation between the expression of DPEP1 and ASCL2 in colon cancer, according to which we speculated that there was a mutual regulatory relationship between them." (PMID 35670012, 2023).
colon cancer (continued). "This study revealed that ASCL2 was highly expressed in colon cancer stem cells." (PMID 35774798, 2022). "This implies that ASCL2-related cancer stem cell signature could affect the efficacy of colon cancer immunotherapy." (PMID 35774798, 2022). "Therefore, we inferred that an ASCL2-related cancer stem cell signature was likely to affect the efficacy of colon cancer immunotherapy." (PMID 35774798, 2022). "Finally, we transfected ASCL2 over-expression and siRNA plasmids in colon cancer cells, and found ASCL2 positively regulates the expression of c-Myc expression, which is a key gene of the Wnt signaling pathway by western blot." (PMID 35774798, 2022). "This revealed that the ASCL2 could affect immunotherapy response by direct regulation of colon cancer stem cells and indirect regulation of tumor-infiltrating immune cells." (PMID 35774798, 2022). "(E) Western blot of Ascl2 and Lgr5 showing enriched colon stem cells in miR-34a-/- colon tumors." (PMID 30543324, 2018). "(D) Immunofluorescence of Ascl2 showing enriched colon stem cells in miR-34a-/- colon tumors." (PMID 30543324, 2018). "Ascl2 may be a potential target for the inhibition of colon cancer progenitor cells, and functions through a miR-302b-related mechanism." (PMID 22384170, 2012). "Thus HT-29 and LS174T cells were chosen for functional evaluation of Ascl2 in colon cancer progenitor cells after gene knockdown by RNA interference." (PMID 22384170, 2012). "Immunohistochemical staining was used to determine whether Ascl2 protein was expressed in human colon mucosa and colon cancer." (PMID 22384170, 2012). "Thus, we concluded that Ascl2 knockdown results in tumor growth arrest by miRNA-302b-related inhibition of colon cancer progenitor cells." (PMID 22384170, 2012). "Given the link between ASCL2 and early onset colon cancer, further studies to explore HMGA1 and ASCL2 are warranted." (PMID 39895630, 2025). "Silencing HMGA1 in 2 human colon cancer cell lines (SW620, SW480) by lentiviral-mediated delivery of short hairpin RNA (shRNA) or CRISPR/Cas9 represses ASCL2, demonstrating that ASCL2 expression depends on HMGA1." (PMID 39895630, 2025). "Strikingly, most of the Wnt genes upregulated by HMGA1 in our murine model are also upregulated in human colon cancer, including the WNT effectors, ASCL2, AXIN2, CTNNB1, MYC, EPHB2, CD44, and ETS2 and the WNT receptors, LGR5, LRP5, and LRP6." (PMID 39895630, 2025). "Further, in human colon cancer, HMGA1 and ASCL2 are coexpressed and upregulated along with downstream Wnt pathway genes." (PMID 39895630, 2025). "Bioinformatics analysis showed that ASCL2 and DPEP1 were both markedly expressed in colon cancer tissues and had a significantly positive correlation." (PMID 35670012, 2023). "Recently, it has been reported that retinoic acid receptor-related orphan receptor α (ROR α), Achaete scute-like 2 (ASCL2) and DNA inhibitor binding/differentiation 2 (Id2) bind the promoter region of SEMA3F in colon cancer." (PMID 36119535, 2022). "The results of the IC50 values indicated a significant increase in the drug sensitivity of both ASCL2-LOW and DUSP4-HIGH to WNT pathway inhibitor in colon cancer." (PMID 35774798, 2022). "We performed GSEA comparing colon cancer samples with high expression and low expression of ASCL2 and DUSP4 using TCGA dataset to identify pathways correlated with ASCL2 and DUSP4." (PMID 35774798, 2022). "The large majority of colon cancers express both LGR5 and ASCL2 and the expression of these markers was positively correlated." (PMID 29652830, 2018). "The levels of expression of the bona fide colon cancer WNT-TCF activity biomarker AXIN2, as well as the WNT-regulated stem cell markers LGR5 and ASCL2, were determined by RT-qPCR in transduced cells in vitro and in subcutaneous xenografts." (PMID 26939070, 2016). "However, the role of Ascl2 in colon cancer progenitor cells remains unknown." (PMID 22384170, 2012).
colon cancer (continued). "Thus, Ascl2 may be a regulatory factor that controls the fate of colon cancer progenitor cells." (PMID 22384170, 2012). "In human colon cancer cells, HMGA1 directly induces ASCL2 by recruiting activating histone marks." (PMID 39895630, 2025). "Together, our results establish HMGA1 as an epigenetic gatekeeper of ASCL2 and Wnt signals, inflammation, and a stem-like state in colon cells with APC inactivation, highlighting HMGA1 as a promising potential therapeutic target in colon cancer." (PMID 39895630, 2025). "To determine if HMGA1 activates the ASCL2 promoter, we cloned the human ASCL2 promoter sequence (–2.5 kb from the TSS) upstream of the luciferase reporter gene and transfected this construct into colon cancer cell lines (SW620, SW480)." (PMID 39895630, 2025). "Ectopic expression of Ascl2 had no influence on liver metastases in the two colon tumor models." (PMID 37591954, 2023). "Re-expression of RAI2 in human colon cancer cells (HCT116 and LoVo) suppressed the fluorescent activity of Wnt signaling, increased the phosphorylation and inhibited nuclear translocation of β-catenin, with down-regulation of target genes like c-Myc, CyclinD1, ASCL2, and LGR5." (PMID 35299743, 2022). "Therefore, DPEP1/ASCL2 could form a positive feedback loop regulation to maintain high expression levels of DPEP1 and ASCL2 in colon cancer cells, which may explain why DPEP1 induced an increase in drug resistance in colon cancer cells in an ASCL2‐dependent manner." (PMID 35670012, 2023). "Restoration in ASCL2 levels results in a partial rescue of proliferation and full rescue of clonogenicity in both cell lines, suggesting that ASCL2 mediates some, but not all, effects of HMGA1 in these colon cancer cells." (PMID 39895630, 2025). "Furthermore, qRT-PCR analysis for Wnt target genes (including cMyc, Ascl2, Axin2, CD44, CD1, Sox17, Wif1 and Tiam1) did not identify any significant differences between the colonic tumours isolated from both cohorts of mice." (PMID 25881306, 2015). "In addition, in another public transcript data set (GSE76342) for the colon cancer cell line LoVo with or without metformin treatment, we found that metformin inhibited expression of the CSC markers Lgr5, ASCL2, EPHB3, OLFM4, BMI1, Lrig1, TERT, CD44, and CD133." (PMID 32911743, 2020).
gastric cancer (9 papers, 2017 to 2026). A primary or metastatic malignant neoplasm involving the stomach. "Aberrant upregulation of ASCL2 was previously associated with 5-FU resistance in gastric cancer." (PMID 38252116, 2024). "In vivo study we found Bufalin decreased ASCL2 expression in the transplanted tumors and induced gastric cancer xenograft apoptosis." (PMID 29805736, 2018). "For further research, we hypothesize that the ASCL2 is correlated with stomach carcinoma progression." (PMID 36008864, 2022). "As the expression of the ASCL2 in the tumor tissues is significantly increased, we hypothesized that the ASCL2 is probably related to the stomach carcinoma progression." (PMID 36008864, 2022). "Further bioinformatics analysis of the ASCL2 in STAD patients using the cBioPortal and GEPIA system shows that the ASCL2 may be related to CNTNAP3, CLIP1, C9orf84, ARIH2, and IL1R2 mutations and involved in stomach carcinoma prognosis, which requires further verification in future studies." (PMID 36008864, 2022). "Compared with other gastrointestinal (GI) cancers (gastric cancer, MSI CRC, and esophageal cancer), ASCL2 is specifically upregulated in MSS CRC." (PMID 33628843, 2021). "Nevertheless, in stomach carcinoma, the potential role of ASCL2 in inflammation via TLR4 activation or its pathways has not been completely clarified." (PMID 36008864, 2022). "To explore whether ASCL2 is activated epigenomically, we compared MSS CRC with MSI CRC, gastric cancer, EAC, and ESCC." (PMID 33628843, 2021). "Furthermore, bufalin inhibited ASCL2 expression and down-regulated the expression of invasion-related genes such as MMP2, MMP9, and vimentin, thereby suppressing epithelial-mesenchymal transition (EMT) in gastric cancer." (PMID 29805736, 2018). "The ASCL2 shows a negative correlation with inflammation, and TLR4 reveals a positive correlation with gastric cancer." (PMID 36008864, 2022). "The ASCL2 shows a negative correlation with H. pylori-induced gastrointestinal inflammation, uses resistin as a regulator of inflammation, activates TLR signaling and TLR4 cascade, and positively correlates with gastric cancer by GSEA." (PMID 36008864, 2022).
adenoma (7 papers, 2013 to 2025). A neoplasm arising from the epithelium. "As in the Apc+/Min-FCCC model, most sporadic CRCs arise following the loss of APC, resulting in the formation of microadenomas, adenomas, and ultimately carcinomas with elevated Ascl2 expression." (PMID 33671373, 2021). "The strong immune response against the Ascl2/Mash2 self-antigen was associated with strong anti-tumor activity, resulting in a significant reduction in colon microadenomas and adenomas." (PMID 33671373, 2021). "Ascl2, which is a master regulator of cellular stemness in Lgr5+ cells, is dramatically overexpressed during spontaneous colon tumorigenesis in Apc+/Min-FCCC mice and in humans (>7-fold in adenomas; >10-fold in carcinomas)." (PMID 33671373, 2021).
breast carcinoma (5 papers, 2014 to 2025). "ASCL2 was an independent indicator in recurrent breast cancer patients, which can also estimate the risk of relapse in breast cancer." (PMID 40963862, 2025).
colitis (4 papers, 2020 to 2025). Inflammation of the colon. "Our results showed that the mRNA levels of ISC maker genes, including Lgr5, Olfm4 and Ascl2, were significantly increased in the colon of colitis mice after L-fucose treatment." (PMID 36432480, 2022). "The overexpression of Ascl2 attenuated colitis symptoms in mice by reducing inflammation and decreasing Th17 cell infiltration in Ascl2-overexpressing experimental colitis mouse models, revealing that Ascl2 is a potential therapeutic target for the treatment of colitis." (PMID 40002370, 2025). "Likewise, real-time quantitative PCR showed that the mRNA expression of the ISC marker genes Lgr5, Olfm4 and Ascl2 was increased in the L-fucose-treated colitis mice." (PMID 36432480, 2022). "Administration of QCWZD expedited ISCs proliferation, as evidenced by significant compensated the expressions of stem cell markers such as Lgr5 and achaete-scute like-2 (Ascl2) in colon of colitis mice in the present of QCWZD when compared to mice in DSS group." (PMID 34557102, 2021). "Furthermore, achaete-scute complex homologue 2 (Ascl2) inhibits Th17 cell differentiation and restrains their pathogenicity via promoting Blimp-1-dependent IL-10 production, whereas Ascl2 was shown to be significantly downregulated in human IBD and experimental colitis." (PMID 32403220, 2020).
colonic adenocarcinoma (3 papers, 2012 to 2022). "Downregulation of Ascl2 using RNA interference in cultured colonic adenocarcinoma HT-29 and LS174T cells reduced cellular proliferation, colony-forming ability, invasion and migration in vitro, and resulted in the growth arrest of tumor xenografts in vivo." (PMID 22384170, 2012). "Ascl2 mRNA and protein levels were measured in HT-29, LS174T, Caco-2, Lovo, and SW480 human colonic adenocarcinoma cell lines." (PMID 26307678, 2015).
glioma (3 papers, 2009 to 2024). A benign or malignant brain and spinal cord tumor that arises from glial cells (astrocytes, oligodendrocytes, ependymal cells). "As the function and mechanism of the ASCL2‐ATG9B axis was revealed in gliomas, we further considered the relationship between ASCL2 and ATG9B in glioma samples." (PMID 35882624, 2022). "LC3 fluorescent dots measured by fluorescence microscopy and autophagosomes visualized by transmission electron microscopy were increased in glioma cells overexpressing ASCL2." (PMID 35882624, 2022). "The promoter of ATG9B (2 kb upstream of the transcriptional start site) was inserted into the dual‐luciferase reporter plasmid, and glioma cells with ASCL2 overexpression exhibited higher transcriptional activity than those with Ctrl overexpression." (PMID 35882624, 2022). "mRNA and protein expression of stemness markers were elevated in glioma cells with ASCL2 relative to Ctrl." (PMID 35882624, 2022). "By analyzing markers of autophagy and autophagosomes, we found that knockdown of ATG9B in ASCL2‐overexpressing glioma cells significantly blocked ASCL2‐mediated upregulation of autophagy." (PMID 35882624, 2022). "IHC of ASCL2 was performed in 338 glioma specimens, ROC analysis was performed to determine the cutoff value, and Kaplan–Meier survival analysis indicated that patients with high ASCL2 expression exhibited poorer overall survival than those with low ASCL2 expression." (PMID 35882624, 2022). "We constructed overexpression plasmids to transfect glioma cells, and only elevated ASCL2 could significantly increase the mRNA and protein expression of ATG9B, which was consistent in multiple glioma cells transfected with an ASCL2 overexpression lentivirus." (PMID 35882624, 2022). "Enforced expression of ASCL2 in glioma cells improved colony formation and self‐renewal abilities." (PMID 35882624, 2022). "Our study unveiled that ASCL2 improved basal autophagy to maintain stemness through transcriptional regulation of ATG9B and that elevated ASCL2 promoted glioma progression in vivo." (PMID 35882624, 2022). "As expected, overexpression of ASCL2 caused increased autophagic flux, as evidenced by conversion from LC3‐I to LC3‐II and degradation of SQSTM1 in multiple glioma cells, but did not significantly affect ATG7 and BECN1." (PMID 35882624, 2022). "To demonstrate this hypothesis, we first analyzed the expression of core autophagy genes in glioma cells overexpressing ASCL2 relative to control cells, and ATG9B was significantly elevated in two glioma cell lines." (PMID 35882624, 2022). "The correlation of ASCL2 and CTNNB1 (β‐catenin) was significant in TCGA gliomas dataset." (PMID 35882624, 2022). "Furthermore, inhibition of ATG9B also impeded ASCL2‐mediated elevation of colony formation and self‐renewal abilities, which implied that in addition to autophagy, ASCL2 also regulated the stemness phenotype in an ATG9B‐dependent manner, it was also verified in primary glioma stem cells." (PMID 35882624, 2022). "Thus, our results rule out ASCL2 and ASCL3 and the more distantly related TRIM genes as potential glioma tumor suppressors within the genomic region analyzed." (PMID 19250537, 2009).
intestinal cancer (3 papers, 2016 to 2022). "In line with human intestinal cancers, Lgr5 and Ascl2 were overexpressed in all three tumor models indicating an increased number of stem-like cells as a result of aberrant Wnt signaling." (PMID 27811361, 2016). "As a transcription factor, ASCL2 also has been identified as a WNT/β-catenin target gene, and which was shown to be expressed in the mouse intestinal crypt as well as human and mouse intestinal cancers." (PMID 36266266, 2022).
lung carcinoma (3 papers, 2014 to 2024). "IMT1B treatment blunted cell proliferation in both SCN prostate and lung cancer cell lines with approximately twice the potency in the POU2F3/ASCL2 subtype." (PMID 39589879, 2024). "JMJD2A was reported to transcriptionally repress ASCL2 in vitro and CHD5 in lung carcinoma." (PMID 24886710, 2014). "In addition to ASCL2 gene, JMJD2A was shown to transcriptionally repress other genes, such as the tumor suppressor gene CHD5 in a lung carcinoma model." (PMID 24886710, 2014).